KL (klotho)
Diseases named in the same sentence as KL in open-access papers (continued):
Sharing a sentence is not in itself a finding about the gene and the disease.
acute kidney injury (82 papers, 2012 to 2025). Sudden and sustained deterioration of the kidney function characterized by decreased glomerular filtration rate, increased serum creatinine or oliguria. "In humans, low Klotho levels in blood, urine, and kidney have been strongly associated with acute kidney injury, with Klotho levels correlating with resilience to kidney damage." (PMID 39940672, 2025). "The Klotho gene is closely associated with the diagnosis and treatment of acute kidney injury (AKI)." (PMID 40595835, 2025). "Klotho deficiency leads to apoptosis and increased oxidative stress in renal tubular cells, which is particularly evident in acute kidney injury." (PMID 40595835, 2025). "At the same time, supplementation with artificial recombinant Klotho has shown promise in improving acute kidney injury caused by contrast agents, ischemia–reperfusion injury, and sepsis." (PMID 38584258, 2024). "In experimental models, a decrease in Klotho has been associated with acute renal failure 45, suggesting its role as a possible biomarker." (PMID 38169578, 2024). "Mice deficient in Klotho had a higher likelihood of developing COVID-19-induced acute kidney injury and Klotho-derived peptide 1 attenuated the viral-induced tubular injury." (PMID 39861814, 2024). "A Chinese emergency cohort study showed that serum cystatin C, kidney injury molecule-1, neutrophil gelatinase-associated lipocalin, klotho, and fibroblast growth factor 23 are valuable in the early prediction of sepsis-related acute kidney injury." (PMID 36060071, 2022). "Alpha klotho protected lung and lung epithelial cells through increased antioxidant capacity while alpha klotho deficiency in acute kidney injury increased oxidative damage to these cells due to decreased antioxidant capacity." (PMID 27429711, 2016). "Thus, soluble Klotho protein attenuates kidney damage and preserves kidney function in an ischemia–reperfusion injury model causing acute kidney injury, which is a state of acute Klotho deficiency." (PMID 36829798, 2023). "However, cotreatment with cisplatin and pyrocatechol significantly alleviated the loss of klotho caused by cisplatin-induced acute kidney injury." (PMID 36193072, 2022). "Meanwhile, acute kidney injury (AKI)/CKD are states of systemic Klotho deficiency, making Klotho a sensitive biomarker of impaired renal function." (PMID 35509269, 2022). "More experimental and human studies have confirmed that Klotho levels are reduced in the kidneys, blood, and urine following acute kidney injury and renal ischemia-reperfusion injury." (PMID 41239227, 2025). "It's demonstrated that Sp1 can activate Klotho in renal tubular epithelial cells, and overexpression of SP1 will alleviate fibrosis in HK-2 by enhancer Klotho expression, as well as alleviate acute kidney injury." (PMID 40034749, 2025). "In different disease models, only one study investigated the correlation between GDF-15 and Klotho protein in acute kidney injury and kidney fibrosis and found that GDF-15 and Klotho protein levels have a strong correlation." (PMID 38672115, 2024). "In comparison with the normal rats, as it was expected, the abundance of Klotho in the renal tissue was reduced by 30% in the animals with renal failure (1.00 ± 0.03 vs. 0.70 ± 0.06-fold change vs. control, p < 0.05)." (PMID 38673780, 2024). "Further in vivo research illustrated that during renal failure, Klotho in bone was important in inducing FGF-23 production since long bone-specific Klotho ablation mice failed to increase FGF-23 level." (PMID 39465174, 2024). "A recent study reported that Klotho was involved in the positive regulation of lipid metabolism in renal tubular epithelial cells in acute kidney injury." (PMID 38584258, 2024). "Administration of exogeneous klotho protein or inducing endogenous production has led to promising outcomes in animal models, including reduction in the progression of acute kidney injury to CKD or attenuation of ischaemic renal injury." (PMID 39281418, 2024).
acute kidney injury (continued). "What comes as a pleasant surprise is that klotho can promotes recovery in acute kidney injury of mice." (PMID 37924002, 2023). "They revealed a novel potential use of urinary extracellular vesicles (uEVs) as a new therapeutic strategy for acute kidney injury, highlighting the presence and role of the renoprotective factor Klotho." (PMID 36684427, 2022). "After developing renal failure, adenine-fed and control mice were randomized to receive either Klotho protein or vehicle." (PMID 35813388, 2022). "IRI, which in the present investigation was used as a model for acute kidney injury, resulted in a significant reduction of the potential kidney protective factors, klotho and BMP7." (PMID 34061900, 2021). "A preclinical study using a rat model of ischemic acute renal failure demonstrated that ischemic lesions reduced klotho synthesis immediately, although it recovered after 4 days." (PMID 34758731, 2021). "One study showed that giving hydrogen-rich saline to a mouse model of acute kidney injury upregulated Klotho expression and protected the kidney from further damage." (PMID 34737707, 2021). "In animals, with renal failure, the increase in the renal load of P is accompanied by a reduction in tubular expression of klotho, which generates resistance to the phosphaturic effect of FGF23." (PMID 33498560, 2021). "Fibroblast Growth Factor 23 (FGF23) and Klotho play an essential role in the regulation of mineral metabolism, and both are altered as a consequence of renal failure." (PMID 32188018, 2020). "On the other hand, mice ubiquitously overexpressing Klotho seem to be protected against renal function deterioration in case of acute kidney injury (AKI) as well as in a glomerulonephritis model." (PMID 33585584, 2020). "It has been shown that acute kidney injury (AKI) is a state of transient Klotho deficiency after most cardiac surgeries, hence Myocardial IR-induced AKI could also be responsible for Klotho reduction that requires further investigation." (PMID 31096903, 2019). "There was a decreasing trend in Klotho expression with increasing renal failure in that serum from HD subjects inhibited Klotho expression more significantly compared with CKD3 (P<0.05)." (PMID 31519772, 2019). "In pediatric CKD and CKD-T patients, the FGF23 level increase and Klotho level decrease with progressing renal failure, despite well-controlled phosphate levels." (PMID 28795324, 2018). "Klotho is an anti-aging factor mainly produced by renal tubular epithelial cells, and is down-regulated in acute kidney injury." (PMID 28536887, 2018). "The ischemic acute renal failure was exacerbated through the downregulation of renal Klotho, whereas an induction of kl gene expression protected tissue from I/R injury." (PMID 30671457, 2018). "The other positive predictor of s-Klotho in our study was serum Ca as if a regulatory role of s-Klotho would be present even in case of renal failure." (PMID 25873958, 2015). "It is therefore proposed that the use of epigenomic editors which activate antifibrotic genes, including RASAL1, KL, and IL-10, may represent a promising approach for the treatment of acute kidney injury and fibrosis." (PMID 40650152, 2025). "The expression of Klotho is reduced in cases of acute kidney injury." (PMID 38584258, 2024). "Urinary Klotho has been reported to serve as a possible early biomarker of acute kidney injury." (PMID 39861814, 2024). "This confirmed that Klotho gene expression is down-regulated in acute renal failure." (PMID 35656176, 2022). "The calpain-mediated AIM2 inflammasome signaling pathway and distinct interaction between calpain and Klotho may provide a potential novel preventative and therapeutic target for acute kidney injury." (PMID 35155498, 2022).
acute kidney injury (continued). "In the injected mice, activation of the follistatin (Fst), utrophin, or klotho genes was shown to increase the muscle mass or mitigate the muscle wasting phenotype (e.g., Duchenne muscular dystrophy) or, in the case of klotho, to attenuate the disease phenotype of acute kidney injury." (PMID 35152318, 2022). "Decreased Klotho expression has been shown to drive accelerated aging and renal failure." (PMID 33687326, 2021). "Klotho has also been shown to cause the degradation of TLR4, the receptor for LPS, via a deglycosylation-associated proteolytic process and thus attenuate LPS-induced acute kidney injury." (PMID 33478014, 2021). "More clinical research has reported that a deficiency of Klotho may be an early biomarker for CKD and acute kidney injury." (PMID 32581850, 2020). "Finally, direct administration of exogenous, soluble klotho has also been proven effective for increasing circulating klotho levels, as well as protecting against acute kidney injury and CKD." (PMID 32260373, 2020). "Our study showed that serum Klotho protein has the potential to be a useful biomarker for the early detection and prognosis of acute kidney injury (AKI) in patients with craniocerebral injuries." (PMID 40595835, 2025). "Moreover, the analysis of post-mortem sepsis–acute kidney injury biopsies showed a significant reduction in the abundance of Klotho mRNA, and a study in critically ill patients found lower levels of urine Klotho (normalized by urine creatinine) in samples obtained 24–48 h after AKI diagnosis." (PMID 37892163, 2023). "Moreover, klotho is increased in the early stage of renal failure as a compensatory hormone." (PMID 37507659, 2023). "However, scanty, available papers report reduced urinary Klotho in patients with renal failure and in animals selectively null for nephron Klotho, both results confirming our hypothesis." (PMID 25873958, 2015). "For example, administration of GDF15 increased klotho expression and reduced FGF23 levels in an experimental model of acute kidney injury (AKI) through folic acid." (PMID 40563333, 2025). "Some authors have suggested a kidney-protective effect of Klotho by disrupting the beclin 1/Bcl-2 complex, upregulating autophagy activity and protecting against IRI-induced acute kidney injury in mice." (PMID 36829798, 2023). "Significantly, two mouse models of acute kidney injury (AKI), namely bilateral ischemia reperfusion injury, and unilateral ischemia and unilateral nephrectomy, have demonstrated that klotho/s-klotho induction of autophagic flow also contributes to attenuate AKI progression to CKD." (PMID 34950686, 2021). "It has been observed in several studies that there is a decrease in Klotho levels (mRNA and protein) both in animal models and individuals with CKD and renal failure." (PMID 35056905, 2021). "Similarly in another research, it has been confirmed that the repletion of Klotho restrained the progression of acute kidney injury (AKI) to CKD in a mouse model of renal I/R injury." (PMID 30671457, 2018). "The objective of the current review was to focus on the suitability and validity of Klotho, CYR61 and YKL-40 as ideal predictive biomarkers for acute kidney injury." (PMID 27759760, 2017). "Numerous recently published studies have illustrated the impact of acute kidney injury (AKI) on the susceptibility of cardiomyocytes to the induction of arrhythmias and a heart failure phenotype, which is correlated with elevated levels of FGF23 and reduced Klotho levels." (PMID 40863356, 2025). "In conclusion, this study shows that the inhibition of Calpain 1 and 2 activity by calpeptin plays a nephroprotective role in ischemia/reperfusion-induced acute kidney injury by suppressing AIM2 and NLRP3 inflammasome activation and by upregulating Klotho protein." (PMID 35155498, 2022). "Moreover, the IP-IB assay showed significant differences in serum klotho levels among stage 3 CKD, acute kidney injury, and end-stage renal disease groups." (PMID 32677951, 2020).
acute kidney injury (continued). "In a nephrotoxic acute kidney injury (AKI) mouse model, klotho expression was also reduced, and blockage of TNF-related weak inducer of apoptosis (TWEAK), which is a member of the TNF superfamily, was able to revert kidney klotho levels and preserve renal function." (PMID 30348110, 2018). "Therefore, in the current study, in the early stage of renal failure, the possible compensatory increase in klotho may decrease the plasma level of FGF23, attenuate its destructive effect on TBS, and modulate the effect of renal failure on TBS." (PMID 37507659, 2023). "However, not all of the protective effects of Klotho in kidney involve regulation of autophagy: one study showed that Klotho can mitigate sepsis-induced acute kidney injury without affecting levels of autophagy in the kidney." (PMID 34737707, 2021). "Klotho may be an early clinical biomarker of acute and chronic renal injury CKD as its diminution precedes changes of other well-established markers/factors involved in the progression of renal failure." (PMID 22121479, 2012). "Acute kidney injury (AKI) is a state of high FGF23 and low Klotho." (PMID 37892163, 2023). "Kidney Klotho is downregulated in sustained hypertension, diabetes mellitus, and CKD models as well as in experimental ischemia-reperfusion-induced or nephrotoxic acute kidney injury (AKI)." (PMID 24386260, 2013). "Moreover, splicing of the two (standard functional and alternative) mRNA transcripts of Klotho in humans is dysregulated especially in acute kidney injury (AKI), favoring the nonfunctional alternative transcript." (PMID 33478014, 2021).
cardiac hypertrophy (65 papers, 2014 to 2025). "By reducing cardiac hypertrophy, fibrosis, protein hyperacetylation, and molecular markers of aging, sKL restores both diastolic function and exercise tolerance in aged and Klotho-deficient models." (PMID 40894259, 2025). "Experimental models have demonstrated that administering sKlotho to Klotho-deficient mice prevents cardiac hypertrophy and increases survival." (PMID 41141519, 2025). "In the context of cardiovascular disease, low levels of Klotho have been associated with a number of adverse outcomes, including myocardial ischemia, cardiac hypertrophy, sinus node dysfunction and sudden cardiac death." (PMID 40134808, 2025). "Myocardial hypertrophy was alleviated after injecting a transgene encoding Klotho intravenously in Klotho-deficient CKD mice." (PMID 38409304, 2024). "Intravenous delivery of a transgene encoding soluble Klotho mitigated cardiac hypertrophy in the Klotho-deficient CKD mice." (PMID 35872753, 2022). "In an experimental study, Klotho-deficient CKD mice had accelerated cardiac hypertrophy and cardiac fibrosis compared to wild-type CKD mice." (PMID 35872753, 2022). "High phosphate was associated with lower Klotho levels, leading to cardiac hypertrophy and fibrosis." (PMID 35448889, 2022). "The influence of aging on cardiac hypertrophy is well known, and a similar phenotype has been reported in Klotho deficient mice." (PMID 36353482, 2022). "Klotho deficiency in CKD results not only in cardiac hypertrophy but is involved in cardiac fibrosis development." (PMID 32106499, 2020). "The clinicians emphasize that Klotho is associated with reduction of renal fibrosis, cardiac hypertrophy, and remodeling." (PMID 30671457, 2018). "Intravenous delivery of a transgene encoding soluble klotho attenuated cardiac hypertrophy in the klotho-deficient CKD mice." (PMID 29506503, 2018). "Xieet al. showed that klotho-deficient CKD mice have aggravated cardiac hypertrophy and cardiac fibrosis compared with wild-type CKD mice." (PMID 29506503, 2018). "The association between FGF23 and cardiac remodeling in klotho-deficient animals suggests that FGF23 affects cardiac hypertrophy and fibrosis only in states of high phosphate and klotho deficiency." (PMID 29977226, 2018). "An experimental study demonstrated more severe cardiac hypertrophy, fibrosis and dysfunction in heterozygous Klotho-deficient CKD than in wild-type CKD mice." (PMID 30200452, 2018). "The study of animal model revealed that Klotho-deficient mice developed an exaggerated pathological cardiac hypertrophy and remodeling after an overstimulation by isoproterenol (ISO)." (PMID 30671457, 2018). "Most animal study results have suggested that klotho deficiency is associated with cardiac hypertrophy." (PMID 29506503, 2018). "It was reported that Klotho-deficient mice develop heart hypertrophy caused by increased circulating Fgf23." (PMID 24797667, 2014). "In addition to direct renal effects, Klotho deficiency triggers and exacerbates disorders of mineral metabolism, secondary hyperparathyroidism, vascular calcification, and cardiac hypertrophy and fibrosis." (PMID 40134808, 2025). "In addition to cardiac hypertrophy, klotho deficiency in CKD is implicated in developing cardiac fibrosis." (PMID 40559238, 2025). "Nevertheless, preclinical studies conducted on Klotho knockout mice have revealed that Klotho deficiency is associated with impaired cognition, shorter lifespan, cardiac hypertrophy, vascular calcification, multi-organ atrophy and fibrosis and growth retardation." (PMID 38213484, 2024). "Moreover, Klotho-deficient mice have illustrated higher rates of vascular calcification, cardiac hypertrophy, cognitive impairment, hypercalcaemia, hyperphosphataemia, multi-organ atrophy and osteopenia." (PMID 38213484, 2024). "It appears that Klotho deficiency may contribute to the generation of cardiac hypertrophy observed in patients CKD stages G3a–b and G4; however, publications on this issue are limited." (PMID 32188018, 2020).